CUL3 (cullin 3)
Diseases named in the same sentence as CUL3 in open-access papers (continued):
Sharing a sentence is not in itself a finding about the gene and the disease.
viral infection (6 papers, 2013 to 2025). "Immunoblotting results demonstrated that these viral infections significantly induced the appearance of additional Cullin 3 bands." (PMID 40396757, 2025). "We first validated the initially observed interactions between NSP1 and Rbx1, Cul1, Cul3 and β-TrCP by co-immunoprecipitation (IP) of transiently overexpressed NSP1s, Rbx1 and Cul3 and in the context of virus infection." (PMID 27706223, 2016). "The data indicated that the active Cul3 protein is involved during the early stages of virus infection to support efficient E1A gene expression." (PMID 24260437, 2013). "Overexpressing Cul3 conversely inhibits viral infection in a dose-dependent manner." (PMID 32882949, 2020). "Alternatively, A55 may sequester Cul3 and prevent the ubiquitylation and/or proteasomal degradation of proteins that are normally ubiquitylated/degraded upon viral infection." (PMID 30819806, 2019). "In addition, we show that inactivation of the Cullin-3 protein activity reduces adenovirus E1A gene expression during early phase of virus infection." (PMID 24260437, 2013). "Gene ontology classes of the predicted cellular targets of HPV16-miR-H1-1 suggest important roles in host cell interactions of HPV 16, such as the cell cycle process (CUL3, CYP26B1, MAP3K11, PBRM1, SMC1A), especially the M phase (CYP26B1, PBRM1, SMC1A), which is important for viral infection." (PMID 23936163, 2013). "Unlike closely related protein family members Cul1, Cul4 and Cul5, which are hijacked by HIV-1 to support viral infection, our data demonstrate that Cul3 acts as a negative regulator of HIV-1 infection and further elucidate the mode of action by which Cul3 exerts this restrictive effect on HIV-1." (PMID 32882949, 2020).
gastric cancer (5 papers, 2017 to 2023). A primary or metastatic malignant neoplasm involving the stomach. "Enhanced neddylation of CUL3 can inhibit the growth of gastric cancer cells by the KEAP1-CUL3-Nrf2 axis, and induce tumor cell apoptosis by producing more ROS." (PMID 37777749, 2023). "In a functional context, circular cullin 3 (circCUL3) significantly enhances ECAR in gastric carcinoma cells." (PMID 37532687, 2023). "As increased nuclear levels of NRF2 protein have been documented in gastric cancer cell lines and tissues, but the frequency of somatic mutations in NFE2L2, KEAP1 and CUL3 is low, it is likely that NRF2 can be upregulated by other mechanisms in GC." (PMID 33276631, 2020). "However, our data showed that the silencing of CUL3 or FLIP/L did not influence K48‐linked polyubiquitination of caspase‐8, and the silencing of CUL3 also did not change the interaction between TRAF2 and caspase‐8 in gastric cancer cells." (PMID 28972304, 2017).
Intellectual disability (5 papers, 2020 to 2024). "Altered spatial learning/memory may have some face validity for humans with Cul3 loss-of-function mutations because some of these patients also exhibit intellectual disability." (PMID 37428799, 2023). "De novo loF mutations in CUL3 are an important cause of ASD, motor deficits, and intellectual disability in humans." (PMID 34031387, 2021). "While intellectual disabilities and social behaviors are aspects of ASD frequently studied in humans and model systems, our analysis of Cul3 neuronal knockdown flies also revealed two more unusual phenotypes: increased sensitivity to both starvation and hyperoxia, an induced oxidative stress." (PMID 38233464, 2024).
Anxiety (4 papers, 2021 to 2025). Intense feelings of nervousness, tension, or panic often arise in response to interpersonal stresses. "Altogether, our results indicate Cul3 heterozygous deletion does not generally alter the locomotor, sensory, anxiety-related, or olfactory ability in mice." (PMID 37428799, 2023). "Motor defects of Cul3+/− mice, however, do not affect exploratory behavior in the open field, nor on the elevated plus maze, where Cul3+/− animals do not show differences in anxiety-like behaviors." (PMID 34031387, 2021).
cognitive deficits (4 papers, 2021 to 2023). "Autism spectrum disorder and intellectual impairment have been seen in FHHt patients with CUL3 variants as well." (PMID 37845702, 2023). "Our findings provide evidence that Cul3 deletion in cholinergic neurons both affects their firing rate in the BF and generates loss of social preference and cognitive deficits." (PMID 36693858, 2023). "In addition to these abnormalities, Cul3 ablation in cholinergic neurons caused a profound impairment in temporal order object recognition memory; this may model cognitive deficits frequently observed in ASD." (PMID 36693858, 2023). "Cul3+/− mice displayed social and cognitive deficits, as well as hyperactivity, accompanied by reduced dendritic growth and cortical neuronal activity." (PMID 37575562, 2023). "Conditional Cul3 ablation in cholinergic neurons of mice (ChatCRECul3F/+) recapitulated ASD-like social and sensory gating phenotypes and caused significant cognitive impairments, with diminished activity of cholinergic neurons in the basal forebrain (BF)." (PMID 36693858, 2023). "Cortical hypofunction was also found after ChAT-specific Cul3 ablation and stimulation of cholinergic projections from the BF to the prefrontal cortex (PFC) mitigated cognitive deficits." (PMID 36693858, 2023). "In mouse, constitutive Cul3 haploinsufficiency leads to motor coordination deficits as well as ASD-relevant social and cognitive impairments." (PMID 34031387, 2021).
colorectal cancer (4 papers, 2022 to 2025). A primary or metastatic malignant neoplasm that affects the colon or rectum. "According to The Cancer Genome Atlas (TCGA) database, the decreased expression of KLF5, KLHL13, and CUL3 in colorectal cancer tissues was predictive of poorer overall survival." (PMID 41443421, 2025).
COVID-19 (4 papers, 2021 to 2023). A disease caused by infection with severe acute respiratory syndrome coronavirus 2. "Therefore, it is possible that UBA52 and CUL3 may also play a role in the pathogenesis of COVID-19 and HFRS coinfection through their involvement in the ubiquitin-proteasome system." (PMID 37234545, 2023). "CUL3 was identified to be regulated by both miR-5197-3p and miR-3529-5p; importantly, it has roles in endothelial cell function and angiogenesis, which may be of interest in relation to the strong endothelial-related responses observed in COVID-19." (PMID 33467206, 2021). "The protein–protein interaction (PPI) network of DEGs was then constructed and six genes named RAD51, ALDH1A1, UBA52, CUL3, GADD45B, and CDKN1A were identified as the commonly dysregulated hub genes among HFRS and COVID-19." (PMID 37234545, 2023). "Our study uncovered six genes named RAD51, ALDH1A1, UBA52, CUL3, GADD45B, and CDKN1A were found to be commonly dysregulated among HFRS and COVID-19." (PMID 37234545, 2023). "This may be related to the fact that the Nrf2 inhibitor complex, i.e., Keap1/Cul3, can direct IκBα to ubiquitination and degradation, and in patients who did not survive COVID-19, the level of Keap1 showed a downward trend." (PMID 37686388, 2023).
glioblastoma (4 papers, 2014 to 2022). The most malignant astrocytic tumor (WHO grade IV). "CUL3 mediates neurofibromin destabilization, which underlies glioblastoma pathogenesis." (PMID 28924174, 2017). "The ubiquitin ligase complex which controls both the regulated destruction and pathogenic destabilisation of neurofibromin was recently identified in glioblastomas as a Cullin 3(Cul3)/kelch repeat and BTB domain-containing 7 complex." (PMID 25026295, 2014). "Additionally, the expression of sonic hedgehog (SHH) signaling-related proteins (SHH, smoothened homolog (Smo) and glioblastoma (Gli)) and CUL3 was tested with western blotting." (PMID 35715796, 2022). "For example, CUL3-KBTBD7 has been shown to destabilize neurofibromin 1 (NF1) in glioblastoma cells, making it a potential therapeutic target for glioblastoma." (PMID 33990333, 2021).
renal fibrosis (4 papers, 2019 to 2024). A final common manifestation of a wide variety of chronic kidney diseases characterized by glomerulosclerosis and tubulointerstitial fibrosis. "Cul3 disruption led to progressive interstitial inflammation, functionally relevant renal fibrosis and death." (PMID 30872636, 2019). "Furthermore, a study uncovers that increased interactions of Keap1 with CUL3 could promote renal fibrosis by reducing Nrf2 level." (PMID 34227919, 2021).
diabetes (3 papers, 2022 to 2025). "A recent study shows the levels of CUL3 and its neddylated derivatives were substantially increased in the aortic tissues and heart of the streptozotocin-induced mice, and dysfunction of CUL3 RING E3 ubiquitin ligase caused vasoconstriction and increased sodium reabsorption in diabetes mice." (PMID 35715796, 2022). "Cancer tissues had lower levels of KLF5, KLHL13, and CUL3 but higher levels of CEP57L1 than paracarcinoma counterparts, which was exaggerated by the presence of diabetes." (PMID 41443421, 2025). "In a cohort of cancer patients, KLF5, KLHL13, and CUL3 levels were lower, but CA and CEP57L1 were higher in cancer tissues, compared with noncancerous counterparts, which were more obvious in those with diabetes." (PMID 41443421, 2025).
epilepsy (3 papers, 2014 to 2023). A brain disorder characterized by episodes of abnormally increased neuronal discharge resulting in transient episodes of sensory or motor neurological dysfunction, or psychic dysfunction. "We found proteins from this network were also enriched in multiple mouse models (Fmr1-/y, 22q11.2+/-, Cul3-/-), and the level of enrichment in these models was consistently higher for the epilepsy network than for the global proteome disrupted in 16p11.2dup/+ mice." (PMID 36808153, 2023). "Previous expression studies have not reported the differential expression of CUL3 in epilepsy patients." (PMID 24959624, 2014).
non-small cell lung carcinoma (3 papers, 2020 to 2025). A group of at least three distinct histological types of lung cancer, including non-small cell squamous cell carcinoma, adenocarcinoma, and large cell carcinoma. "KEAP1/NFE2L2/CUL3 represented a mechanism of resistance to tyrosine kinase inhibitor in patients with EGFR-mutant non-small cell lung cancer." (PMID 35371318, 2022).
Obesity (3 papers, 2022 to 2026). Accumulation of substantial excess body fat. "Findings support that supplementation and repair of deleted CSN subunit genes or CUL3 as well as CUL4 by CRISPR technology emerge as novel therapeutic approaches for the treatment of specific types of obesity." (PMID 40149914, 2025). "Damage to CSN/CUL3/CUL4A genes is associated with diverse diseases, including obesity." (PMID 40149914, 2025). "KLHL3 promotes substrate ubiquitination through interaction with CUL3-based E3 ligases, and WNK kinases are well-known substrates for KLHL3;13,14,17 however, the role of KLHL3 interactions with other substrates in obesity is unknown." (PMID 36028759, 2022).
oral squamous cell carcinoma (3 papers, 2020 to 2024). "In conclusion, our study revealed that lactate derived from cancer-associated fibroblasts promotes the CSCs phenotype in oral squamous cell carcinoma through the DLG5/CUL3/MST1 signaling axis." (PMID 39605072, 2024). "In HPV(−) oral cavity SCC (OSCC), we found NFE2L2(NRF2), KEAP1, and CUL3 genes were altered in 11%, 4%, and 4% of tumors, respectively." (PMID 38335300, 2024).
osteosarcoma (3 papers, 2017 to 2021). A usually aggressive malignant bone-forming mesenchymal neoplasm, predominantly affecting adolescents and young adults. "Among the other six Cullins, only CUL4A was slightly overexpressed (~1.4–1.7-fold induction) in osteosarcoma cells, but not the other five Cullins, including CUL1, CUL2, CUL3, CUL5 and CUL7." (PMID 28446751, 2017).
Sepsis (3 papers, 2019 to 2022). Sepsis is defined as life-threatening organ dysfunction caused by a dysregulated host response to infection. "In vivo and in vitro results strongly supported that PQQ relieved sepsis-induced acute liver injury, inflammatory and oxidative stress damage and cell apoptosis by repressing CUL3 expression." (PMID 34227919, 2021). "Based on knowledge above, this current work was designed to explore the role of PQQ in sepsis and determine the molecular function of CUL3 in the pathogenesis of sepsis." (PMID 34227919, 2021). "Among them, miR-29b-3p, miR-15b-5p, miR-15a-5p, miR-107, XIST, miR-19a-3p, miR-16-5p, miR-19b-3p, miR-92a-3p, and CUL3 were closely related to the pathogenesis of sepsis-induced AKI." (PMID 31658856, 2019). "The pathogenesis of sepsis-induced AKI may involve the miR-15a-5p–X-inactive specific transcript – Cullin 3 regulatory axis with induction of renal cell apoptosis, according to earlier findings." (PMID 35305556, 2022). "This phenomenon prompted the potential role of CUL3 in the progression of sepsis." (PMID 34227919, 2021). "Mechanistically, PQQ treatment may mitigate sepsis-induced acute liver injury through downregulating CUL3 expression." (PMID 34227919, 2021). "Mechanically, results delineated that PQQ may ameliorate sepsis-induced acute liver injury through suppressing CUL3 expression." (PMID 34227919, 2021). "To conclude, CUL3 may act as the promoting factor during the development of sepsis." (PMID 34227919, 2021). "To conclude, the current study will develop novel insights into the molecular function of CUL3 in the pathogenesis of sepsis and highlight the role of PQQ in sepsis therapies." (PMID 34227919, 2021).
atherosclerosis (2 papers, 2022 to 2024). A disease characterized by the build-up of fatty material and calcium deposition in the arterial wall resulting in partial or complete occlusion of the arterial lumen. "Emerging evidence supports the notion that CUL3 might regulate the proliferation, migration and phenotypic transformation of VSMCs in atherosclerosis by modulating Hedgehog signaling pathway." (PMID 35715796, 2022). "Specifically, we reported that Cullin 3, an E3 ubiquitin ligase, ubiquitinates and degrades ABCA1 in promoting diet-induced atherosclerosis." (PMID 38537695, 2024).
bladder cancer (2 papers, 2013 to 2023). "Immunostaining of tissue arrays containing independent series of bladder cancer patients served to assess the associations of a selected protein, Cul3, with clinicopathological variables." (PMID 23308193, 2013). "Cul3 was revealed as a candidate contributing to the aggressive phenotype of T24T modifying cytoskeleton remodelling and as a bladder cancer biomarker correlating with poor outcome." (PMID 23308193, 2013). "Further focused designed studies are warranted to dissect the clinical relevance of Cul3 expression patterns in specific bladder cancer subgroups and address their specific clinical outcome endpoints." (PMID 23308193, 2013). "Thus, combination of -omic approaches, functional and clinical analyses identified Cul3 as a novel candidate related to bladder cancer aggressiveness." (PMID 23308193, 2013). "Thus, the SILAC approach identified that Cul3 modulated the aggressive phenotype of T24T cells by modifying the expression of cytoskeleton proteins involved in bladder cancer aggressiveness; and played a biomarker role for bladder cancer progression, nodal metastasis and clinical outcome assessment." (PMID 23308193, 2013). "Cul3 was selected from the top over-expressed candidates in T24T not previously characterized in bladder cancer for which we had available reagents for further studies." (PMID 23308193, 2013).
cervical cancer (2 papers, 2016 to 2022). A primary or metastatic malignant neoplasm involving the cervix. "Here, we report that DRAK1 protein was specifically degraded through K48-linked polyubiquitination induced by CUL3/SPOP E3 ubiquitin ligase in paclitaxel-resistant cervical cancer cells." (PMID 35194034, 2022). "For instance, downregulation of miR-141 increases CUL3 expression in Hirschsprung's disease, and miR-19 targets CUL5 to regulate proliferation and invasion of cervical cancer cells." (PMID 26840256, 2016).
colitis (2 papers, 2021 to 2022). Inflammation of the colon. "Simultaneous depletion of ACLY partially rescued CUL3 deficiency-induced defects in iTreg differentiation and colitis alleviation." (PMID 34491895, 2021). "Importantly, knocking down Acly in iTreg (Cul3-/-+siAcly) cells prior to the adoptive transfer rescued CUL3-deficiency-induced failures in colitis alleviation." (PMID 34491895, 2021). "In addition, the expression levels of pro-inflammatory cytokines IL-1 and IL-6, and chemokines CXCL1 and CXCL2 were upregulated by O-GlcNAcylated STAT3 in BMMs from CUL3-deficient mice, thus contributing to azoxymethane-induced colitis and colitis-associated cancer." (PMID 35203353, 2022). "When we injected recipient mice with iTreg (Cul3-/-) cells, less alleviation in colitis was observed as compared to that in iTreg (WT) group." (PMID 34491895, 2021). "When we removed CUL3 to block ACLY degradation, iTreg differentiation and colitis alleviation by adoptive iTreg cells in mice were compromised." (PMID 34491895, 2021).
endometrial cancer (2 papers, 2015 to 2023). Primary or metastatic malignant neoplasm involving the endometrium (mucous membrane that lines the endometrial cavity). "In this study, we demonstrated that SPOP forms a functional CUL3-SPOP-RBX1 E3 ubiquitin ligase complex which targets ERα for ubiquitination and proteasomal degradation in endometrial cancer cells." (PMID 25766326, 2015).
head and neck carcinoma (2 papers, 2019 to 2021). A carcinoma that arises from the head and neck region.
hepatocellular carcinoma (2 papers, 2021 to 2026). A malignant tumor that arises from hepatocytes. "In hepatocellular carcinoma, elevated Cul3 expression correlates with poor patient prognosis and advances liver cancer development by disrupting the assembly of the SKP1-Cullin-1-F-box protein (SCF) and lipid accumulation." (PMID 41492274, 2026).
Hirschsprung disease (2 papers, 2016 to 2020). Hirschsprung disease (HSCR) is a congenital intestinal motility disorder that is characterized by signs of intestinal obstruction due to the presence of an aganglionic segment of variable extent in the terminal part of the colon. "A recent study shows that miR-141 downregulates the CUL3 level in Hirschsprung’s disease (HSCR), and some studies demonstrate that miR-141 is also highly associated with malignancies such as gastric cancer, colon cancer, nasopharyngeal carcinoma and pancreatic cancer." (PMID 32555680, 2020).